MARCKS (myristoylated alanine rich protein kinase C substrate)
Diseases named in the same sentence as MARCKS in open-access papers (continued):
Sharing a sentence is not in itself a finding about the gene and the disease.
tumor (continued). "Abnormal MARCKS signals may participate in malignant deformation, uncontrolled proliferation, migration, and invasion of malignant tumor cells." (PMID 35401213, 2022). "Furthermore, upregulated expression of the tumor-suppressive miR-34a was found to directly inhibit MARCKS in a sequence-specific manner and decreased the viability of drug-resistant cells upon treatment with MM-associated chemotherapeutic agents." (PMID 33958003, 2021). "To this end, we investigated the interactome of signaling molecules which may be cooperating with MARCKS to promote tumor aggressiveness." (PMID 33754052, 2021). "While it is understood that MARCKS impacts the overall carcinogenesis as well as plays a part in determining the disease outcome in blood cancers, we are still at an early stage of interpreting the pathophysiological roles of MARCKS in neoplastic disease." (PMID 33958003, 2021). "Therefore, we performed immunohistochemistry analyses of CRC tumor samples from nine patients to establish the presence of phosphor-MARCKS in CRC." (PMID 32056006, 2020). "According to these analyses, 6 out of 12 tested tumor samples are devoid of MARCKS." (PMID 32056006, 2020). "Here interfering with MARCKS phosphorylation with the aim of MARCKS re-activation could define a novel avenue in individualized tumor therapies." (PMID 32056006, 2020). "Genetic or pharmacological inhibition of GAP43 or MARCKS could be employed to specifically interfere with tumor growth." (PMID 31058089, 2019). "In IBC samples, MARCKS staining was observed in some cases within the dermal tumor emboli." (PMID 28009981, 2017). "Additionally, MARCKS was highly expressed in normal ovary epithelial cells compared with tumor epithelial cells." (PMID 29295532, 2017). "MARCKS expression was then measured on the 502 tumor samples." (PMID 28009981, 2017). "Our observations suggest that inhibition of MARCKS and the related signaling network to target stromal activation could be a potential approach in targeting the cooperative tumor stroma of OC." (PMID 27081703, 2016). "Furthermore, in accordance with that MARCKS was upregulated in tumor stroma after chemo-intervention, we found that suppression of MARCKS sensitized CAFs to cytotoxic agents, supporting its role in regulating chemosensitivity." (PMID 27081703, 2016). "We further investigated whether MARCKS activation in fibroblasts facilitates their tumor promoting function." (PMID 27081703, 2016). "The miR-21 family has been significantly examined for tumor metastasis without affecting cell proliferation and targets myristoylated alanine rich protein kinase C substrate (MARCKS), a protein which is associated with actin cytoskeleton." (PMID 27992561, 2016). "Thus, in stromal fibroblasts, MARCKS activation was necessary for the maintenance of their supportive role in facilitating tumor cell growth and invasion." (PMID 27081703, 2016). "However, the molecular mechanism underlying increased phosphorylation of MARCKS at Ser159/163 (phospho-MARCKS) and its functional consequence in neoplastic disease remain to be established." (PMID 26015406, 2015). "A positive correlation between tumor grade and phospho-MARCKS was established (p = 0.005)." (PMID 26015406, 2015). "In addition to this anti-apoptotic effect, we also suggest a novel function of phospho-MARCKS to promote angiogenic activity, thereby tumor growth and metastasis." (PMID 26015406, 2015). "Univeriate analysis indicated that high MARCKS expression (mRNA z-score > 1) was significantly associated with HER2 positivity (p = 0.0004), ER and PR negativity in IHC data (both p < 0.0001), higher nonsynonymous tumor mutation burden (p = 0.0019), and younger age at diagnosis (p < 0.0001)." (PMID 40940979, 2025). "Since most signaling proteins, including MARCKS protein, interact with other proteins for driving biological processes 11, we investigated whether MARCKS forms oncogenic complexes for executing its pro-tumor activities." (PMID 33754052, 2021).
tumor (continued). "We found more frequent stromal MARCKS expression in tumor samples (77%) than in normal samples (22%), and correlation with shorter overall survival in uni- and multivariate analyses, suggesting that MARCKS inhibition might represent a new therapeutic approach in EOC." (PMID 29295532, 2017). "Given the increase in MARCKS expression as OC progresses or under chemo-intervention, we hypothesized a potential role of MARCKS in OC metastasis and disease recurrence by activating tumor stroma." (PMID 27081703, 2016). "Indeed, our study demonstrates that elevated phospho-MARCKS augments a variety of signaling pathways and tumor behaviors, including invasion/metastasis, induction of angiogenesis and paclitaxel resistance in TNBC cell lines such as MDA-MB-231 and MDA-MB-468 cells." (PMID 26015406, 2015). "A stringent cross-comparison identified five proteins (PSAP, MARCKS, eEF1A1, DDX39B, and RACK1) as consistently and differentially regulated across tumor stages." (PMID 42064067, 2026). "Although these findings suggest that MARCKS expression may be linked to features of hormone receptor insensitivity and tumor biology, Kaplan–Meier survival analysis did not reveal a significant difference in overall survival between MARCKS high and low groups within HER2 positive patients." (PMID 40940979, 2025). "Consistently, we also identified MARCKS as a HER2 interactor in an additional HR-negative, HER2-positive tumor specimen (Case 3), supporting its potential relevance in more aggressive, hormone receptor-negative disease contexts." (PMID 40940979, 2025). "The expression levels of the genes CD36, CXCL14, DAB2, MARCKS, ENPEP, and TIMP1 in normal, tumor, and metastatic tissues were analyzed using various statistical methods." (PMID 40565366, 2025). "Only two transcripts, MARCKS (Myristoylated Alanine Rich Protein Kinase C Substrate) and TXNIP (Thioredoxin Interacting Protein) were present in all three gene sets in the C2 tumor cell cluster." (PMID 36788228, 2023). "Deserve to be mentioned, NK CD56 bright cells were positively related to ALKBH7, which proved to be correlated with CXCL12 expression in a pancreatic pre-tumor cell model and MARCKS expression in HCC, meanwhile, all of them expressed in various tumor." (PMID 35980268, 2022). "Whereas GAP43 and MARCKS are oncogenic, tumor suppressive functions have been ascribed to BASP1 and in part to MARCKS depending on the cell type." (PMID 31058089, 2019). "In distinct human tumors, mainly oncogenic properties are described for GAP43 and MARCKS, whereas for BASP1 a general tumor suppressive function has been reported." (PMID 31058089, 2019). "In these patients, tumor expression of miR-126 and miR-451 and that of the biomarkers PTEN, MARCKs, FGFRL-1, SNAIL-1, P63, and k-RAS were reduced." (PMID 29371906, 2018). "We analyzed correlations between the binary MARCKS IHC status and prognostic clinicopathological features of samples including patients’ age, FIGO stage, pathological type and grade, and macroscopic tumor residue after debulking surgery." (PMID 29295532, 2017). "Suppression of MARCKS attenuates CAF activity and their tumor-supporting role in 3D organotypic culture and an OC murine xenograft model." (PMID 27081703, 2016). "MARCKS inhibition was shown to suppress the AKT signaling, a pathway that controls nearly all the malignant behaviors of tumor cells." (PMID 27081703, 2016). "Negative methylation/expression correlations were also found for HDAC4 (a chromatin modifier), ERBB3 (a known oncogene), as well as MARCKS and CXCR4; genes known to induce tumor cell invasion and therapeutic resistance in other tumor types." (PMID 26963385, 2016).
tumor (continued). "Taken together, our data showed here that the MARCKS expression supports the emergence of a CAF-like cell state, impacting tumor progression through stroma–tumor communication that alters the tumor-supporting role of CAFs." (PMID 27081703, 2016). "In addition to blocking phospho-MARCKS-associated functions, it is possible that MANS peptide may suppress paclitaxel-induced inflammation directly or indirectly, thereby improving the anti-tumor ability of paclitaxel." (PMID 26015406, 2015). "Extensive research has revealed that miR-21 is involved in proliferation, the cell cycle, metastasis and the chemosensitivity of tumor cells by targeting several tumor suppressor genes, including PTEN, MARCKS, PDCD4 and Cdc25A." (PMID 24260069, 2013). "We found increased ABCB1 expression in MARCKS negative CRC patient tumor samples and established CRC cell lines." (PMID 32056006, 2020). "In fact, MARCKS staining (total MARCKS) was absent in three tumor samples and markedly reduced in another three samples in contrast to strong MARCKS staining in adjacent normal tissue (left)." (PMID 32056006, 2020). "Furthermore, miR-21 can downregulate several tumor suppressor genes e.g., PDCD4, MARCKS, and RECK metalloproteinase inhibitor, TPM1 and hence stimulating tumor initiation, invasion, and intravasation." (PMID 32308936, 2020). "The tumor suppressive functions of BASP1 and MARCKS could be exploited to expand the spectrum of future innovative therapeutic approaches to inhibit growth and viability of susceptible human tumors." (PMID 31058089, 2019). "Several studies in other solid cancers have suggested the involvement of MARCKS in tumor progression and resistance, and its interest as novel therapeutic target." (PMID 28009981, 2017). "Tissue microarrays of local prostatectomy samples from a cohort of biochemical recurrent and non-biochemical recurrent tumours were assayed for MARCKS protein expression." (PMID 29069765, 2017). "Moreover, MARCKS were overexpressed in all tumor tissue-derived cell subpopulations, with its expression levels progressively increasing with the differentiation of UTUC tumor cells." (PMID 38903524, 2024). "The prognostic relevance of MARCKS and phosphatase and tensin homolog (PTEN) protein expression as a surrogate marker of metastasis-free survival (MFS) was evaluated by immunohistochemistry (IHC) in a retrospective series of archival tumor samples derived from 180 IBC patients and 355 nIBC patients." (PMID 36139501, 2022). "It was observed that both miR-144-5p and miR-144-3p had tumor inhibitory effects by targeting several oncogenes in squamous NSCLC including neuronal calcium sensor 1 (NCS1), solute carrier family 44 member 5 (SLC44A5), and myristoylated alanine rich protein kinase C substrate (MARCKS) genes." (PMID 32276343, 2020). "Subsequently, IHC analysis of the obtained tumor sections confirmed the diminished stromal staining of MARCKS activation and AKT signaling, as well as the attenuated stromal Twist1 expression and the resultant αSMA staining, in the sh-MARCKS group compared with that of the sh-NC co-injection group." (PMID 27081703, 2016). "Taken other line of evidence together, a possible role of miR-21 as an oncogene has been hypothesized, including proliferation, cell cycle, metastasis, and chemosensitivity of tumor cells by targeting several tumor suppressor genes such as PTEN, MARCKS, PDCD4, and Cdc25A." (PMID 22792096, 2012). "Of note, this inverse correlation of MARCKS and ABCB1 expression was also observed in three tumor samples with highly phosphorylated MARCKS (data not shown), suggesting that the phosphorylation status of MARCKS is relevant for its impact on ABCB1 function." (PMID 32056006, 2020). "Here, as a first step and to validate our initial observation, we evaluated and compared MARCKS protein expression in 133 IBC and 369 non-IBC tumor samples collected from French and Tunisian patients." (PMID 28009981, 2017).
tumor (continued). "Our objective was to validate at the protein level the overexpression of MARCKS in IBC in a large series of clinical samples (133 IBC and 369 non-IBC) and to search for correlations with tumor features." (PMID 28009981, 2017). "The differences between tumor and metastatic tissues were gene-specific; for instance, no significant changes were observed in some genes, such as CD36 and ENPEP (p = 0.42), whereas significant changes were detected in others, such as MARCKS (p = 5.40 × 10−7)." (PMID 40565366, 2025). "Besides their functions in neurons, GAP43, MARCKS, and BASP1 are also expressed in non-neuronal cells, and display intrinsic oncogenic or tumor suppressive functions." (PMID 31058089, 2019). "However, non-tumor lung expression of miR-21, PTEN, MARCKs, TPM-1, PDCD4, and SPRY-2 did not significantly differ between LC-COPD and LC patients." (PMID 29371906, 2018). "Moreover, MARCKS and ABCB1 expression were inversely correlated in six CRC tumor samples with reduced or absent MARCKS expression and in adjacent normal tissue: Normal tissue showed high MARCKS and low ABCB1 expression and tumor tissue displayed low MARCKS and high ABCB1 expression." (PMID 32056006, 2020).
infection (8 papers, 2008 to 2024). The state of being infected such as from the introduction of a foreign agent such as serum, vaccine, antigenic substance or organism. "We also observed that siRNA-mediated knockdown of either MARCKS or PKC-η expression in A549 cells reduced pMARCKS levels by >3-fold in response to 30 or 60 min of infection with Bt CDC2721121, compared to host cells treated with non-targeting siRNA (siR-CTL)." (PMID 28638804, 2017). "Our results show that infection with unopsonized B. thailandensis specifically activates PKC-η regulation of MARCKS function on both transcriptional (expression) and post-transcriptional (phosphorylation) levels to enable pathogen survival within the host." (PMID 28638804, 2017). "We observed that inhibition of PKC-η or MARCKS function by siRNA or functional mutant expression reduced the efficiency of Bt CDC2721121 infection in A549 cells." (PMID 28638804, 2017). "We observed that there was a decrease in MARCKs band intensity with increase in time period from 30 to 120 min post-infection in the membrane fraction of HMEECs infected with WT P. aeruginosa." (PMID 26973629, 2016). "Densitometric analysis revealed a fivefold increase in MARCKs expression in the cytosol at 120 min post-infection compared to at 30 min post-infection." (PMID 26973629, 2016). "On the other hand, MARCKS band intensity increased with increase in post-infection time period in the cytosolic fraction." (PMID 26973629, 2016). "Quantification of this data confirmed that there was a 3.5-fold decrease in the presence of MARCKs in the membrane fraction at 120 min post-infection compared to at 30 min post-infection." (PMID 26973629, 2016). "By immunoblot, infection-related enhancement of MARCKS phosphorylation manifested as a retarding of MARCKS mobility during SDS-PAGE." (PMID 24068923, 2013). "Only the changes in the expression levels of five histone genes and the MARCKS gene could be considered common indicators of 12 h infection in all analyzed cell cultures." (PMID 37998351, 2023). "Furthermore, we show that mRNA levels of MARCKS are induced in miR-21−/− BMDM following infection with L. monocytogenes." (PMID 28589100, 2017). "Microglial actins in astrocyte-co-cultures were down-regulated after HIV-1/VSV infection and the proteins related to actin binding, polymerization and stability, including MARCKS, moesin, Wiskott-Aldrich syndrome protein (WAS) and gelsolin, were all up-regulated." (PMID 18575609, 2008). "Since MARCKS is a prominent substrate of PKC which is shown by our data to be sensitive to M. avium infection, we also investigated whether infection with 10 MOI of M. avium for 8 hours would result in phosphorylation of serine 163 within the effector domain of MARCKS protein." (PMID 39413095, 2024). "MARCKS inhibition may offer a strategy to limit excess neutrophil recruitment to sites of infection or inflammation through inhibition of adhesion and migration, while still preserving neutrophil host defense mechanisms such as phagocytosis and respiratory burst." (PMID 38398044, 2024). "Altogether, our data suggest that MARCKS activation is dependent on PKC-η function, and both proteins are involved in Burkholderia-induced host cell pathology following infection." (PMID 28638804, 2017). "Additional studies warrant further investigation of MARCKS regulation in CF and non-CF cells under both basal conditions and after infection of M. avium." (PMID 39413095, 2024). "We found that both MARCKS and ATG7 transcript levels were reduced ~2- and ~5-fold, respectively, in cells depleted of PKC-η, compared to control siRNA-treated cells (CTL) upon infection with unopsonized Bt CDC2721121." (PMID 28638804, 2017). "Infection with Y. enterocolitica also led to an increase in MARCKS phosphorylation, suggesting that multiple Gram-negative pathogens can activate the PKC-η/MARCKS pathway during infection." (PMID 28638804, 2017).
infection (continued). "A549 cells pre-incubated with mannan exhibited a ~1.5–2-fold decrease in pMARCKS levels following infection with Bt CDC2721121, compared to infected cells not treated with mannan (CTL), suggesting that MARCKS phosphorylation is at least partly dependent on MR engagement by the pathogen (light gray)." (PMID 28638804, 2017). "While infection of lung epithelial cells with unopsonized Gram-negative bacteria stimulated phosphorylation of Ser175/160 in the MARCKS effector domain, siRNA-mediated knockdown of PKC-η expression reduced the levels of phosphorylated MARCKS by >3-fold in response to infection with Bt CDC2721121." (PMID 28638804, 2017).
neurological disorders (6 papers, 2015 to 2025). "For instance, MARCKS has been described to play a role in autoimmunity, neurological disorders, solid tumors and hematological malignancies, fibrosis, as well as respiratory diseases." (PMID 40960646, 2025). "This review will highlight recent advances in understanding the role of MARCKS in the brain, and will propose potential areas for future exploitation both as a window into neuronal physiology and as a therapeutic target in a variety of nervous system disorders." (PMID 26528135, 2015). "Given its critical roles in a variety of brain cell types, it is not surprising that MARCKS has been the subject of intense research into the etiology and treatment of various neurological disorders." (PMID 26528135, 2015).
hematological cancers (3 papers, 2021 to 2022). "It has been reported that MARCKS is associated with the development and progression of hematological cancers." (PMID 35628654, 2022). "Recent evidence indicates that dysregulated expression of MARCKS is associated with the development and progression of hematological cancers." (PMID 33958003, 2021). "Finally, we will discuss the potential therapeutic strategies for addressing the pathological consequences of aberrant MARCKS signaling in hematological cancers." (PMID 33958003, 2021).
neurodegenerative disease (2 papers, 2014 to 2021). A disorder of the central nervous system characterized by gradual and progressive loss of neural tissue and neurologic function. "Thus, loss of adducin function through aberrant phosphorylation of the MARCKS-homology domain may be a contributing factor for human neurodegenerative diseases." (PMID 25416060, 2014).